ENSG00000286248 (novel transcript, antisense to P2RX7)
Gene: Long non-coding RNA gene on chromosome 12 (121,177,919 to 121,191,477, reverse strand). Ensembl gene ENSG00000286248.
Gene Ontology:
Biological process: SRP-dependent cotranslational protein targeting to membrane, signal sequence recognition
Cellular component: signal recognition particle, endoplasmic reticulum targeting